ZNF143 (zinc finger protein 143)
Diseases named in the same sentence as ZNF143 in open-access papers (continued):
Sharing a sentence is not in itself a finding about the gene and the disease.
glioma (4 papers, 2019 to 2025). A benign or malignant brain and spinal cord tumor that arises from glial cells (astrocytes, oligodendrocytes, ependymal cells). "As a TF, ZNF143 has also been shown to be associated with the survival, proliferation, differentiation, migration, and invasion of human glioma cells." (PMID 38950180, 2024). "ZNF143, interestingly, has been seen to mediate the Hippo/YAP signaling pathway in glioma cells, causing cell growth and migration." (PMID 41281751, 2025). "Firstly, the ZNF143 expression of glioma cells treated with altering levels of A1CF, FAM224A or miR-590-3p expression was examined." (PMID 31186064, 2019). "Downregulation of ZNF143 expression markedly impeded the malignant biological behaviors of glioma cells, affirming the oncogenic role of ZNF143 in glioma cells." (PMID 31186064, 2019). "The proliferation, migration and invasion abilities of glioma cells were elevated, while the percentages of apoptotic cells were diminished in the pre-miR-590-3p + ZNF143 (+) group versus the pre-miR-590-5p + ZNF143 (+)-NC group." (PMID 31186064, 2019). "In the present study, the endogenous expression of A1CF, FAM224A, miR-590-3p and ZNF143 were investigated in glioma tissues and cell lines." (PMID 31186064, 2019). "Western blot analysis showed that ZNF143 was overexpressed in glioma tissues and cells compared with NBTs and NHA." (PMID 31186064, 2019). "In our further studies, the ASAP3 and MYB expression of glioma cells treated with altering miR-590-3p and ZNF143 expression levels was detected." (PMID 31186064, 2019). "To validate our assumption, we firstly detected the expression of ASAP3 and MYB in glioma cells treated with altered expression levels of miR-590-3p and ZNF143 expression." (PMID 31186064, 2019). "In conclusion, the A1CF/FAM224A/miR-590-3p/ZNF143 positive feedback loop acts as a critical regulator in the malignant progression of glioma cells, providing a novel molecular target for glioma therapy." (PMID 31186064, 2019). "The ZNF143 expression of glioma cells after ZNF143 overexpression or knockdown was showed." (PMID 31186064, 2019). "Overall, these findings indicated that miR-590-3p could impede ASAP3 and MYB expression by downregulating ZNF143 in glioma cells." (PMID 31186064, 2019). "The present study clarifies that the A1CF-FAM224A-miR-590-3p-ZNF143 positive feedback loop conducts critical regulatory effects on the malignant progression of glioma cells, which provides a novel molecular target for glioma therapy." (PMID 31186064, 2019). "Furthermore, overexpression of ZNF143 reversed the inhibitory effects of overexpressed miR-590-3p on glioma cell progression via upregulating ASAP3 and MYB expression." (PMID 31186064, 2019). "Our data showed that ZNF143 was significantly upregulated in glioma tissues and cell lines." (PMID 31186064, 2019). "Additionally, inhibition of A1CF and FAM224A obviously reduced ZNF143 expression in glioma cells, and upregulation of ZNF143 reversed the prohibitive effects on glioma cells induced by miR-590-3p overexpression." (PMID 31186064, 2019). "Moreover, the downregulation of ZNF143 expression in sh-FAM224A glioma cells was reversed following miR-590-3p knockdown." (PMID 31186064, 2019). "Furthermore, ZNF143 promoted the malignant biological behaviors of glioma cells by stimulating ASAP3 and MYB expression." (PMID 31186064, 2019). "Therefore, ASAP3 and MYB are involved in mediating the regulatory effects of miR-590-3p on glioma cell progression, after being activated by ZNF143." (PMID 31186064, 2019). "Moreover, the expression level of ZNF143 was positively correlated with the pathological grade of glioma." (PMID 31186064, 2019). "Importantly, knockdown of ZNF143 significantly impaired the malignant biological behavior of glioma cells." (PMID 31186064, 2019). "Therefore, we tried to find a new pathway to illustrate the function of ZNF143 in glioma." (PMID 37423952, 2023).
glioma (continued). "Moreover, silencing ZNF143 significantly inhibited the biological behaviour of glioma cells, suggesting that ZNF143 might play an oncogenic role in glioma cells." (PMID 37423952, 2023). "Moreover, ZNF143 participated in miR-590-3p-induced tumor-suppressive activity on glioma cells." (PMID 31186064, 2019). "To date, the mechanisms underlying the function of ZNF143 in glioma have not been elucidated." (PMID 31186064, 2019). "In conclusion, ZNF143 mediates the Hippo/YAP signalling pathway and inhibits the growth and migration of glioma cells by regulating KPNA2." (PMID 37423952, 2023). "Downregulation of ZNF143 and KPNA2 can activate the Hippo signalling pathway and reduce YAP/TAZ expression in human glioma cells, thus inducing apoptosis of human glioma cells and weakening their proliferation, migration and invasion." (PMID 37423952, 2023). "The present study aims to investigate the role of ZNF143 (zinc finger protein 143, the transcription factor of KPNA2) in regulating the effects of KPNA2 on glioma and to explore novel therapeutic targets for glioma." (PMID 37423952, 2023). "The Cell Counting Kit-8 assay, migration and invasion assays, and flow cytometry analysis were conducted to evaluate the function of A1CF, FAM224A, miR-590-3p, ZNF143 and ASAP3 in the malignant biological behaviors of glioma cells." (PMID 31186064, 2019). "Their roles in modulating malignant progression of glioma and the cross-talk between A1CF, FAM224A, miR-590-3p and ZNF143 were elucidated." (PMID 31186064, 2019). "The results above revealed that ZNF143 acted as an oncogene in glioma; however, the potential role of ZNF143 in A1CF and FAM224A induced malignant progression of glioma cells remained to be defined." (PMID 31186064, 2019). "MiR-590-3p could bind to the ZNF143 3′ UTR and repress the expression of ASAP3 and MYB by negative modulation of ZNF143, thereby hindering the malignant progression of glioma cells." (PMID 31186064, 2019). "Moreover, ZNF143 targeted the promoter region of KPNA2 and positively regulated the expression level of KPNA2, which formed a positive feedback loop to jointly regulate the malignant progression of glioma cells." (PMID 37423952, 2023). "However, the basic control mechanism of ZNF143 in glioma has not yet been clarified." (PMID 37423952, 2023).
lung adenocarcinoma (4 papers, 2019 to 2024). A carcinoma that arises from the lung and is characterized by the presence of malignant glandular epithelial cells. "Overexpression of BUB1B can regulate the glycolysis of lung adenocarcinoma cells and bind to zinc finger protein 143 (ZNF143) to promote proliferation, migration and invasion." (PMID 39048649, 2024). "Recently, ZNF143 was reported to be upregulated in lung adenocarcinoma, and was a predictor of high proliferating activity and poor prognosis in patients with lung adenocarcinoma." (PMID 31186064, 2019).
lung carcinoma (3 papers, 2016 to 2023). "However, we did not observe the significant associations between the methylation level of cg17061862 in ZNF143 and lung cancer risk [meta OR (95% CI) = 1.19 (0.96, 1.47), p = 1.20E‐01]." (PMID 33939316, 2021). "In addition, ZNF143 is dramatically upregulated in lung cancer tissues." (PMID 37423952, 2023). "rs1514846 on chromosome 5 was linked to 4 SNPs with CADD scores of over 10, it mapped among histone marks in A549 lung carcinoma cells and changed binding motifs for SP2 and Znf143." (PMID 26959888, 2016).
prostate carcinoma (3 papers, 2011 to 2023). A carcinoma that arises from epithelial cells of the prostate gland. "We conducted a Spearman correlation analysis and found that RIOX2 expression was strongly correlated with ZNF143 expression while moderately with IKZF1 expression in prostate cancers." (PMID 36776320, 2023). "Cisplatin resistant prostate cancer cells grow slowly with overexpression of ZNF143 and increase of G2/M population." (PMID 24213117, 2011). "To assess the function of ZNF143 expression in the cell cycle, we established two cells with forced expression of ZNF143 derived from PC3 prostate cancer cell lines." (PMID 24213117, 2011). "We also previously reported that ZNF143 expression is induced by DNA-damaging agents, and is overexpressed in cisplatin-resistant prostate cancer PC3 cell lines." (PMID 24213117, 2011). "Additionally, we found that ZNF143 knockdown resulted in the downregulation of 152 genes in PC3 human prostate cancer cells." (PMID 24213117, 2011). "We found fluctuations in ZNF143 expression with prostate cancer PC3 cells." (PMID 24213117, 2011). "However, ZNF143 expression was not significantly altered in prostate cancer tissues, indicating it is unlikely a causative factor of RIOX2 upregulation in prostate cancer." (PMID 36776320, 2023).
epilepsy (2 papers, 2023 to 2025). A brain disorder characterized by episodes of abnormally increased neuronal discharge resulting in transient episodes of sensory or motor neurological dysfunction, or psychic dysfunction. "We identified five significant genes (WIPF1, IQSEC1, JAM2, ICAM3, and ZNF143) that had causal relationships with epilepsy." (PMID 37246165, 2023).
liver cancer (2 papers, 2023). An epithelial or non-epithelial malignant neoplasm that arises from the liver. "In addition, RIOX2 expression was found to strongly correlate with ZNF143, which was previously shown to enhance RIOX2 gene expression in liver cancer cells." (PMID 36776320, 2023).
Obesity (2 papers, 2021 to 2024). Accumulation of substantial excess body fat. "In addition, the ZNF143 TF was previously posited as a biomarker for obesity-associated T2D." (PMID 38781157, 2024). "MAP 1B, hsa-mir-4314, hsa-mir-5688, hsa-mir-583, hsa-mir-632, hsa-mir-3176, hsa-mir-4477a, hsa-mir-606, hsa-mir-1343-3p6, SIN3A, ZNF143 and SMARCE1 are the novel biomarkers for pathogenesis of obesity associated type 2 diabetes mellitus." (PMID 33902539, 2021).
ovarian carcinoma (2 papers, 2019 to 2022). A malignant neoplasm originating from the surface ovarian epithelium. "It cannot be excluded that also a nuclear overexpression of ZNF143 protein might be a characteristic feature of chemoresistant cells in low-grade ovarian carcinomas, but this hypothesis needs to be verified in a specifically-designed study." (PMID 30885238, 2019). "The aim of this study was to analyze the expressions of ZNF143 and ZNF281 in tumor tissues and to verify if they correlate with clinicopathological characteristics of borderline ovarian tumors and low-grade ovarian cancers." (PMID 30885238, 2019). "The expression patterns of ZNF143 and ZNF281 identified in this study suggest that both sBOTs and low-grade ovarian cancers might undergo a dynamic epithelial-mesenchymal interconversion." (PMID 30885238, 2019). "Based on the intensity of ZNF143 and ZNF 281 expressions in serous borderline tumors and low-grade ovarian cancers, one may hypothesize that metastasis formation and spread of these malignancies involve some additional, yet unidentified, mechanisms." (PMID 30885238, 2019).
acute lymphoblastic leukemia (1 paper, 2024). Leukemia with an acute onset, characterized by the presence of lymphoblasts in the bone marrow and the peripheral blood. "Screening CD19+ expression in B cell precursor acute lymphoblastic leukemia (BCP-ALL) revealed the contrasting functions of Zinc Finger Protein 143 and Nudix Hydrolase 21 (NUDT21)." (PMID 39538305, 2024).
anemia (1 paper, 2021). A reduction in the number of red blood cells, the amount of hemoglobin, and/or the volume of packed red blood cells. "Furthermore, no Znf143 −/− mice were found among 65 viable progenies, indicating that loss of Znf143 induced a severe embryonic anemia and lethality." (PMID 33397967, 2021).
breast tumor (1 paper, 2014). "ZNF143 levels are rapidly increasing with the breast tumor developmental stage, reaching a 10 times over-expression in cancer stage IV compared to normal tissues." (PMID 24234445, 2014).
kidney tumors (1 paper, 2014). "Instead, in kidney tumors as well as in ovary and prostate tumors, ZNF143 expression stays constant compared to normal tissues." (PMID 24234445, 2014).
liver disease (1 paper, 2022). "ZNF143 plays different roles in HCC and normal liver cells and may be considered as a potential therapeutic target in liver disease." (PMID 35780101, 2022).
ovarian tumors (1 paper, 2019). "In our present study, we observed strong nuclear expression of ZNF143 in most examined ovarian tumors, regardless their histological subtype." (PMID 30885238, 2019). "Nevertheless, it should be emphasized that the majority of ovarian tumors included in this study tested positively for ZNF143 and ZNF281." (PMID 30885238, 2019). "The proportions of the ovarian tumors that tested positively for ZNF143 and ZNF281 were 90 and 57%, respectively." (PMID 30885238, 2019). "However, still little is known about the role of ZNF143 and ZNF281 in the pathogenesis of ovarian neoplasms, and published evidence in this matter is sparse and inconclusive." (PMID 30885238, 2019). "Moreover, we compared the expressions of ZNF143 and ZNF281 in these two groups of ovarian tumors." (PMID 30885238, 2019).
steatosis (1 paper, 2024). Increased lipid within the cytoplasm of cells. "ZNF143 is a transcription factor for NEAT1, and the upregulation of NEAT1 by ZNF143 exacerbated steatosis." (PMID 39872125, 2024). "ZNF143/NEAT1/SND1-mediated ROCK2 signalling upregulation was associated with the downregulation of mitophagy proteins PTEN-induced kinase 1 (PINK1) and Parkin, suggesting that NEAT1 overexpression may contribute to steatosis by impairing mitochondrial repair mechanisms." (PMID 39872125, 2024).
teratocarcinoma (1 paper, 2019). A germ cell tumor characterized by the presence of an embryonal carcinoma component and a teratoma component. "An earlier study also reported that ZNF143 was negatively regulated by miR-590-3p at the post-transcriptional level in teratocarcinoma cells, which upheld our findings." (PMID 31186064, 2019).
cancer (18 papers, 2011 to 2023). A tumor composed of atypical neoplastic, often pleomorphic cells that invade other tissues. "These essential facts lead us to the conclusion that the majority of the genes associated with ZNF143 are linked to the most significant cancer-related pathways." (PMID 36675976, 2022). "Previous studies have shown that ZNF143 expression is associated with cell cycle regulation, cell proliferation, cancer development, and DNA repair." (PMID 35780101, 2022). "Interestingly, expression of ZNF143 decreases in tumor tissues during cancer progression, suggesting a correlation between ZNF143 loss and tumor malignancy, especially in ductal epithelium-originated tumors, such as IDC." (PMID 30935019, 2019). "Multiple studies have reported that ZNF143 has cancer-promoting capabilities in a variety of tumors." (PMID 35847937, 2022). "Zinc finger protein 143(ZNF143), a member of the Krüppel C2H2-type zinc finger protein family, is strongly associated with cell cycle regulation and cancer development." (PMID 35780101, 2022). "We further validated that ZNF143 knockdown had a similar effect on LUAD cancer cell proliferation, migration, and invasion as BUB1B knockdown, which was counteracted by BUB1B overexpression." (PMID 35068350, 2022). "As a key TF, the role of ZNF143 in cancer progression through transcriptional regulation of genes related to DNA replication and cell cycle." (PMID 32318100, 2020). "Many studies utilize knockdown or overexpression methods to evaluate the effect of ZNF143 on cancer cell progression." (PMID 32318100, 2020). "By establishing two forced expression of ZNF143 PC3 cancer cell lines, they found that overexpress genes strongly associated with cell cycle and cell division." (PMID 32318100, 2020). "In recent years, studies have revealed that ZNF143 not only exists in most cancer cells but is also necessary for the normal development of tissues." (PMID 32318100, 2020). "Among the ZNF143-targeted cell cycle-associated kinases, both PLK1 and Aurora kinase B (AUPKB) were overexpressed in a large variety of cancers." (PMID 32076462, 2020). "In the future, it is believed that more and more molecule drugs will be exploited by targeting ZNF143 to treat related cancers." (PMID 32318100, 2020). "Next, we used siRNA approach to selectively knock-down their expression and observed that EIF4A2 expression decreased when knocking-down ZNF143 both in cancer cells." (PMID 31088567, 2019). "ZNF143 was shown to be a determinant of cancer cell motility, as it represses ZEB1, which results in upregulation of E-cadherin to maintain epithelial characteristics of proliferating cancer cells in response to IGF-1." (PMID 30885238, 2019). "Although many controversies surround the relationship between the expression of ZNF143 and cancer malignancy, all the evidence to date suggests that ZNF143 plays a role in cancer development in various experimental systems." (PMID 30933430, 2019). "In the present study, we therefore characterized the relationships between ZNF143 expression and cancer cell survival in invasive ductal carcinoma cells under normal and metabolic stresses, such as fetal bovine serum (FBS) or glucose deprivation." (PMID 30935019, 2019). "Mechanically, EIF4A2 as a transcriptional target of ZNF143 might function via mediating the translation of c-Myc, an oncoprotein that is deregulated in more than 50% human cancers and is related to cancer cell aggressive phenotypes, and drug resistance." (PMID 38023215, 2023). "Additionally, it is understood that ZNF143 is essential for healthy tissue growth and is present in the majority of cancer cells." (PMID 36675976, 2022). "Further analysis indicated that ZNF143 OE may have an important effect on some of the most important signaling pathways that involved in liver regeneration and cancer development, such as the Wnt and Hippo signaling pathways." (PMID 35780101, 2022).